LEP (leptin)
Diseases named in the same sentence as LEP in open-access papers (continued):
Sharing a sentence is not in itself a finding about the gene and the disease.
depression (continued). "Both studies showed an improvement in MDD symptomatology (IDS-SR30 total score), and the second one also found an increase in some depression-related biomarkers, such as urinary Thromboxane B2 (TBX-B2) and substance-P (SUB-P), and plasma endothelin-1 (ET-1) and leptin levels." (PMID 35204235, 2022). "A recent study investigated associations between levels of six cytokines (IL-1β, eotaxin, IL-15, IL-6, TNF-α, and leptin) and chronic multisite pain (CMP) in a sample of people living with HIV, but also incorporated PHQ-9 scores as a measure of depression in their regression models." (PMID 35618889, 2022). "Another possible explanation is that endocrine factors (such as adipokines including leptin, adiponectin, and resistin, secreted by adipose tissues) might be involved in the effect of BWV on depression." (PMID 34955919, 2021). "A study described some pathological pathways common to obesity and depression, such as hyperactivity of the HPA axis, oxidative imbalance, increased levels of inflammatory mediators, leptin, and insulin resistance, reduced BDNF levels and serotonergic signaling dysregulation." (PMID 33673205, 2021). "However, human studies that have investigated circulating leptin levels in relation to AUD and affective disorders, such as anxiety and depression, are conflicting." (PMID 34421692, 2021). "This is important since it was noted that leptin, apart from the already described negative influence, also has a protective effect, e.g., it protects against depression." (PMID 33562571, 2021). "There are inconsistent previous findings regarding the relationship between depression and leptin with studies reporting higher, lower, and similar leptin levels in individuals with depression compared with those without depression." (PMID 33023555, 2020). "The results are not entirely consistent—enhanced leptin was also found in melancholic, but not atypical depression in a POWER (Premenopausal, Osteoporosis, Women, Alendronate, Depression) study." (PMID 33255237, 2020). "There has been a recent increase in studies on the relationship between ghrelin, leptin, and depression; however, they have not reported consistent findings." (PMID 33023555, 2020). "There was a significant negative correlation between plasma leptin levels and depression at T1 and T2 (r = −0.20, P = 0.02 and r = −0.25, P < 0.001, respectively) and with insomnia at T3 (r = −0.20, P = 0.02)." (PMID 31016867, 2019). "Similar to leptin, the expression of p11 (also known as S100A10), involved in the regulation of depression-like behavior and response to antidepressants, was not modified by treatments but its expression levels were higher in the ventral compared to the dorsal hippocampus." (PMID 30804991, 2019). "This absence of anxiolytic effect by leptin in this inflammatory model of depression must be confirmed in future studies." (PMID 30949073, 2019). "It has been emphasized that the anxiety- and depression-like behaviors are correlated with serum leptin levels in non-stressed rat model." (PMID 30551684, 2018). "Depression in women was associated with a larger waist circumference and higher levels of adiposity/T2DM related markers specifically HOMA IR, leptin and TNF-α compared with women without depression." (PMID 29190710, 2017). "This is the first study to examine the serum and tissue leptin-LepRb levels in GC patients with or without depression." (PMID 28316984, 2017). "Recently, a meta-analysis on 1118 participants demonstrated that serum and plasma leptin levels were not altered in subjects with bipolar disorder when compared to healthy controls in mania, in depression, or in euthymia." (PMID 28316984, 2017). "Therefore, the potential role of leptin and the increased prevalence of T2DM and CVD with depression requires further study." (PMID 29190710, 2017).
depression (continued). "A similar scenario has been obtained with respect to depression; depressive GC patients had higher leptin and LepRb mRNA levels than nondepressive patients." (PMID 28316984, 2017). "Such a mechanism would explain the observed negative correlation of leptin in relation to depression, anxiety, and stress in HSS patients during the first treatment phase." (PMID 28030575, 2016). "The POWER study, however, found significant increases in triglycerides, ACTH, and leptin in a melancholic, but not atypical depression, cohort." (PMID 27549765, 2016). "The effect of depression on other lipid biomarkers such as leptin are also not clearly elucidated as both increased and decreased levels have been noted in patients with depression." (PMID 26231223, 2015). "Recently, accumulated studies have demonstrated the negative relationships between leptin level and severity of symptoms of depression in human." (PMID 26183327, 2015). "It is also worth mentioning in connection with depressive mental disorders that leptin, which is connected to TRPC1 (and probably also TRPC3), has antidepressant effects and that impaired leptin production contributes to depression-like phenotypes in a rat model." (PMID 23409712, 2013). "Compatible with this notion, mice rendered obese by a HFD show reduced sensitivity to the antidepressant actions of leptin and to the effects of leptin to increase hippocampal brain-derived neurotrophic factor (BDNF) concentrations (protective against depression) relative to low-fat diet controls." (PMID 24109426, 2013). "After evaluation of depression level study group was divided into groups according to the mood status (A—without depression, B—mild depression, and C—severe depression), and serum concentration of TNF-α, sTNFs, leptin, and IL-6 were measured by ELISA." (PMID 19587822, 2009). "We did not observe differences of serum concentrations of TNF-α, sTNFRs, leptin, and IL-6 between subgroup A and subgroups B and C. It seems that circulating adipokines did not exert influence on depression levels in obese women." (PMID 19587822, 2009). "The aim of the study was to assess serum concentrations of TNF-α, TNF soluble receptors, leptin, and interleukin-6 (IL-6 ) in obese subjects with and without depression." (PMID 19587822, 2009). "Paralleling findings in leptin and ghrelin, adiponectin's involvement in depression pathophysiology might not be adequately reflected in serum levels." (PMID 35633817, 2022). "The association between ↑WS v. depression without ↑WS and leptin PRS was close to the significance threshold [OR = 1.09 (1.04–1.14), p = 2.99 × 10−04] but disappeared when considering GWAS summary statistics of leptin adjusted for BMI." (PMID 32624019, 2022). "In addition, in the pioglitazone group, but not in the placebo group, leptin level was increased in subjects who showed a decrease in depression score, and this correlation was significant." (PMID 32971941, 2020). "Leptin can also increase the expression of BDNF mRNA, activate BDNF-expressing neurons, activate the PI3K-AKT-mTOR pathway to regulate the growth of neurons and regulate stress-induced depression and antidepressant response while reversing the dysfunction in the HPA axis." (PMID 31130833, 2019). "Thus, based on the current results, leptin is not a biomarker for the diagnosis of depression or other mood disorders." (PMID 30367065, 2018). "In addition, we compared the serum and tissue leptin-LepRb levels between GC patients who suffer from depression and those without depression." (PMID 28316984, 2017). "Considering this accumulated information, leptin resistance, a condition in which hyperleptinaemia fails to exert the full physiological effects, interferes with mood and cognition, connecting the inflammatory environment specific to depression and anxiety to metabolic disruption." (PMID 41375608, 2025).
depression (continued). "In addition, leptin was shown to be responsible for the inhibition of the Neuropeptide Y (NPY) neurons, which is known to have a specific anxiolytic and neuroprotective properties, and is proposed to play a critical role in mediating chronic stress in patients with depression." (PMID 31354416, 2019). "However, a recent meta-analysis showed that peripheral levels of leptin did not significantly differ between patients with depression and healthy controls although heterogeneity was large and body mass index of participants across studies emerged as a significant moderator." (PMID 30949073, 2019). "Low CSF levels of leptin were detected in female suicide attempters with MDD, however, the serum leptin levels were not significantly changed in women with postpartum depression." (PMID 30666218, 2018). "Because depression often results in profound alterations in dietary intakes, with either increased or decreased appetite, the observed differences in leptin and ghrelin levels between those with and without depression symptoms may simply reflect such change in dietary habit." (PMID 25079305, 2014). "Because we found no reduction in the odds for men in the highest tertile of leptin (a level comparable to women in the middle tertile of leptin showing a reduction in the odds for depression), the gender difference in leptin levels may not account for the null finding in men." (PMID 25079305, 2014). "It has been suggested that higher levels of leptin may link non-atopic asthma with psychological disorders: levels of leptin are elevated in girls with asthma, in non-atopic-asthmatics, and also in children with symptoms of depression." (PMID 24963333, 2014). "There was a significant difference in median serum leptin levels between PSD patients and no depression cases (32.2 [IQR, 20.8–57.7] v." (PMID 25061971, 2014). "However, in a recent study involving patients with depressive disorders, including MDD and dysthymic disorder, it was observed that baseline leptin levels were significantly elevated in the non-remission group compared to the remission group." (PMID 39629120, 2024).
endothelial dysfunction (187 papers, 2005 to 2026). In vascular diseases, endothelial dysfunction is a systemic pathological state of the endothelium (the inner lining of blood vessels) and can be broadly defined as an imbalance between vasodilating and vasoconstricting substances produced by (or acting on) the endothelium. "The mechanisms underlying leptin-induced endothelial dysfunction involve several interconnected molecular pathways." (PMID 41470134, 2025). "Multivariate analyses confirmed leptin as an independent determinant of endothelial dysfunction, even after adjusting for conventional cardiovascular risk factors." (PMID 41470134, 2025). "Clinical findings have been similarly inconsistent, as associations between leptin and endothelial dysfunction often diminish after adjusting for body mass index (BMI)." (PMID 41470134, 2025). "Elevated leptin levels have been observed in PsA patients, correlating with disease activity and systemic inflammation, thereby contributing to endothelial dysfunction and increased cardiovascular risk." (PMID 40137170, 2025). "Leptin has been linked to endothelial dysfunction, activation of the sympathetic nervous system, and deleterious effects on the underlying vasculature." (PMID 36604367, 2023). "Then, according to leptin’s effects in vessels and its association with proinflammatory events, this adipokine has been mostly linked to endothelial dysfunction and the related vascular pathways." (PMID 37238961, 2023). "Leptin and resistin have been implicated to cause endothelial dysfunction by promoting oxidative stress." (PMID 35711339, 2022). "Excess visceral fat and high systemic levels of adipose tissue (AT) derived mediators such as leptin and other adipokines have also been linked to endothelial dysfunction." (PMID 35837388, 2022). "Leptin was perceived as a risk factor in atherosclerosis progression, which promote endothelial dysfunction, PVAT inflammation and vascular smooth muscle cell phenotypic switching." (PMID 33391033, 2020). "Having established the role of leptin in inducing miR21 and its concomitant repression of miR21 target proteins, it was important to study the role of leptin induced miR21 in causing sinusoidal endothelial dysfunction in our models of NASH." (PMID 25658689, 2015). "Leptin-induced miR21 caused sinusoidal endothelial dysfunction primarily by repressing Grhl3, a protein that has a role in phosphorylating NOS3 and increasing NO bioavailability." (PMID 25658689, 2015). "Experimental data suggest that intact leptin signaling may exert protective effects on the myocardium, whereas chronic hyperleptinemia in humans is associated with endothelial dysfunction, fibrotic remodeling, and adverse metabolic consequences." (PMID 41596265, 2026). "Additionally, adipocytokines secreted by visceral fat, such as leptin and resistin, promote inflammation and endothelial dysfunction, leading to vasoconstriction and increasing the risk of vulnerability and rupture of atherosclerotic plaques." (PMID 40697549, 2025). "Notably, the GG genotype of rs4903273 increases the production of leptin inducing endothelial dysfunction and predisposing the development of preeclampsia." (PMID 38910142, 2025). "Taken together, leptin directly affects endothelial function through multiple molecular pathways, and these altered molecules/pathways could exacerbate the endothelial dysfunction caused by placental soluble factors, worsening the symptoms of preeclampsia." (PMID 39201703, 2024). "Serum leptin has emerged as a potential risk factor for cardiovascular disease due to its proinflammatory, proatherogenic, and prothrombotic effects, which promote endothelial dysfunction." (PMID 34673824, 2021). "In the present study, we tested the hypothesis that the HIV-derived Tat protein induces endothelial dysfunction through alteration in adipose mass and leptin production causing excessive oxidative stress." (PMID 34681637, 2021).
endothelial dysfunction (continued). "In conclusion, using an in vivo approach, our study demonstrated that the HIV transactivator protein Tat contributes to HIV-associated endothelial dysfunction via promoting adipose mass loss, and leptin level reduction leading to an upregulated expression of Nox1 and NoxA1." (PMID 34681637, 2021). "Additionaly, leptin has been associated with proinflammatory and immune stimulatory mechanisms along with ROS formation in obese mice, suggesting these processes as the responsible for the leptin atherogenic effect that leads to endothelial dysfunction." (PMID 26381906, 2015). "We thus argued that leptin, being a proinflammatory adipokine, might play a significant role in causing sinusoidal endothelial dysfunction and disrupted microvasculature in NASH." (PMID 25658689, 2015). "Another theory, based on experiments performed in coronary arterioles, proposes that, paradoxically, leptin causes itself NO-dependent vasodilation and, at the same time, its very presence impairs endothelium-dependent relaxations, that is, produces endothelial dysfunction." (PMID 23573411, 2013). "Moreover, leptin treatment in vivo has been shown to reverse the endothelial dysfunction of leptin-deficient obese (ob/ob) mice by increasing NO bioavailability in vessels." (PMID 20592755, 2010). "Moreover, higher WWI levels may increase stroke risk through the secretion of adipokines such as leptin and adiponectin, which are involved in pro-inflammatory states, oxidative stress, and endothelial dysfunction." (PMID 40013043, 2025). "Furthermore, patients with high BMI frequently develop leptin resistance, and chronically elevated leptin levels may induce endothelial dysfunction, thereby exacerbating microvascular disease risk." (PMID 40655951, 2025). "The possible pathophysiological mechanisms for developing plasma leakage in obese patients with dengue might be due to endothelial dysfunction caused by the chronic release of pro-inflammatory cytokines from elevated leptin levels and production of reactive oxygen species (ROS)." (PMID 34324559, 2021). "Paradoxically, in spite of the elevated leptin levels in obese patients, leptin resistance further contributes to molecular mechanisms in oxidative stress, endothelial dysfunction, and chronic inflammation." (PMID 41597417, 2026). "The pro-inflammatory milieu created by excess adipose tissue, rich in adipokines, like leptin and resistin, exacerbates systemic inflammation and contributes to endothelial dysfunction and atherosclerosis." (PMID 40137170, 2025). "On the one hand, weight gain can lead to increased release of adipokines (e.g., leptin, tumor necrosis factor alpha, retinol-binding protein 4) and cytokines from adipose tissue, leading to inflammatory endothelial dysfunction and metabolic dysfunction." (PMID 41357077, 2025). "Beyond its established role in energy regulation, leptin contributes to endothelial dysfunction through multiple pathophysiological mechanisms." (PMID 41470134, 2025). "It is possible that neuronal dysfunction in the hypothalamus and/or endothelial dysfunction with reduced nitric oxide synthase-3 activity are responsible for increased adipocyte leptin expression in Lrp8Δexon19 mice." (PMID 40722764, 2025). "Experimental work further shows that chronic leptin excess promotes oxidative stress, attenuates NO bioavailability, and induces endothelial dysfunction, particularly under conditions of adiposity and metabolic dysregulation." (PMID 41470134, 2025). "Leptin also enhances endothelial dysfunction by stimulating endothelin-1 production, a potent vasoconstrictor, while simultaneously reducing NO bioavailability through the generation of reactive oxygen species via NADPH oxidase activation." (PMID 41470134, 2025). "The increased PAI-1 and leptin concentrations implied a dysmetabolic proinflammatory state, possibly driven by endothelial dysfunction, further reinforcing the GLUT-1 findings." (PMID 40724955, 2025).